MMP7 (matrix metallopeptidase 7)
Diseases named in the same sentence as MMP7 in open-access papers (continued):
Sharing a sentence is not in itself a finding about the gene and the disease.
leptospirosis (1 paper, 2021). A contagious bacterial infection caused by spirochetes of the genus Leptospira. "In leptospirosis, rLRR20 stimulated the expression of MMP7 and NGAL only at concentrations higher than 6 μM." (PMID 34884937, 2021). "Previous studies have reported that MMP7 and NGAL are also associated with the pathogenesis of leptospirosis." (PMID 34884937, 2021). "The upregulated expression of MMP7 and NGAL may be the mechanism underlying leptospirosis-induced kidney injury, which involves the membrane components of Leptospira." (PMID 34884937, 2021). "The rLRR20-mediated regulation of MMP7 and NGAL was further investigated to verify the correlation between leptospirosis and kidney injury." (PMID 34884937, 2021). "However, the roles of MMP7 and NGAL in leptospirosis pathogenesis are unclear." (PMID 34884937, 2021).
liver cirrhosis (1 paper, 2010). "Lastly, matrix metalloproteinase (MMP)-7(Asp-137) confers risk of liver cirrhosis." (PMID 20170533, 2010).
lung tumors (1 paper, 2015). "Our multiple levels of analysis showed a consistent association between MMP-7 protein expression and LN metastasis, which suggest that MMP-7 mediated degradation of basement membrane could play a central role in lymphatic permeation and infiltrative growth of lung tumors." (PMID 25588786, 2015).
malignant mesothelioma (1 paper, 2020). A malignant neoplasm of the pleura or peritoneum, arising from mesothelial cells. "Among these angiogenesis related biomarkers, we demonstrated that Galectin-1, Mesothelin, shed SDC-1 and MMP-7 are biomarkers that discriminated best between malignant mesothelioma and metastatic adenocarcinomas." (PMID 32731396, 2020). "Stepwise logistic regression based on biomarker levels showed that MMP-7, Mesothelin and Osteopontin are three variables with a higher predictive value for distinguishing malignant mesothelioma from metastatic adenocarcinoma." (PMID 32731396, 2020). "Our data shows that the level of Galectin-1 and mesothelin are significantly higher in MM patients in comparison with metastatic adenocarcinoma patients whereas, shed SDC-1 and MMP-7 levels are significantly decreased in malignant mesothelioma patients." (PMID 32731396, 2020). "Here we show that Malignant mesothelioma patients have significantly higher level of Galectin-1, Mesothelin, Osteopontin, VEGF, shed SDC-1, MMP-7, HGF, NRG1-β1 and TIMP-1 compared to benign patients." (PMID 32731396, 2020). "MMP-7 and angiopoietin-1 have no discriminative capacity to distinguish between malignant mesothelioma and benign effusions." (PMID 32731396, 2020).
malignant pleural mesothelioma (1 paper, 2020). A malignant neoplasm that arises from mesothelial cells in the pleura and shows a diffuse growth pattern. "In our study, a combination of MMP-7, Mesothelin and Osteopontin, showed the best significant model for distinguishing malignant pleural mesothelioma from metastatic adenocarcinoma patients." (PMID 32731396, 2020). "Taken together, candidate biomarkers (Galectin-1, Mesothelin, Osteopontin, shed SDC-1, VEGF, MMP-7, HGF, TIMP-1 and NRG1-β1) identified in the current study could be diagnostic biomarkers for distinguishing malignant pleural mesothelioma and metastatic adenocarcinoma from benign patients." (PMID 32731396, 2020).
metastatic cancer (1 paper, 2020). A carcinoma which has spread from the original site of growth to another anatomic site. "The expression levels of MMP7, MMP13, MMP10, miR-7109-5p and miR-34b in nonmetastatic cancer samples and metastatic cancer samples were measured by qRT-PCR." (PMID 31996191, 2020).
migraine (1 paper, 2022). "Also, our combined gene-based analysis identified three migraine-associated MMPs, including MMP7, MMP20 and MMP27." (PMID 35546551, 2022). "We identified a significant genome-wide pleiotropy between higher levels of MMP7 and migraine risk." (PMID 35546551, 2022). "The other identified pleiotropic effects that link MMPs to migraine risk are pleiotropy at the gene level for MMP1, MMP7 and MMP12, and at the SNPs level for MMP1." (PMID 35546551, 2022). "Our findings of higher levels of MMP7 and VEGFA suggest enhanced permeability of BBB in all migraine patients." (PMID 35546551, 2022).
morbid obesity (1 paper, 2017). An excess of body weight, normally defined as an individual with a body mass index greater than 35 or a body weight greater than one hundred percent of ideal body weight. "Similarly, the MMP-7 -181G allele was associated with a higher MMP-7 level and an increased risk for morbid obesity when compared to AA genotype carriers (0.32 (0.31–0.60) versus 0.18 (0.17–0.24) ng/ml, P = 0.01; OR = 1.67, P = 0.02, resp)." (PMID 29317790, 2017).
muscle tumors (1 paper, 2023). "In addition, 25 DPs are related to muscle tumors; 8 DPs (APOE, FCER1A, FCER2, GSK3B, HSPD1, IL6R, MMP7, and RARRES2) are linked to proliferation of muscle cells." (PMID 36918772, 2023).
muscular dystrophy (1 paper, 2020). Muscular dystrophy (MD) refers to a group of more than 30 genetic diseases characterized by progressive weakness and degeneration of the skeletal muscles that control movement. "Increased MMP-7 activity is observed in a hereditary form of muscular dystrophy, suggesting that upregulated MMP-7 might have detrimental effects on skeletal muscle." (PMID 32375664, 2020).
nephrolithiasis (1 paper, 2023). The presence of a calculus in the pelvis of the kidney; this is most often composed of mineral salts and proteins. "The induced expression of MMP7 with nephrolithiasis could therefore be a valuable indicator of papillary injury associated with this disease." (PMID 37468493, 2023).
oncocytoma (1 paper, 2014). "Intriguing gene expression patterns present in the benign oncocytoma-like regions were the underexpression of metalloproteinases matrix metallopeptidase 1 and matrix metallopeptidase 7 diminishing invasiveness." (PMID 25275525, 2014).
oropharyngeal squamous cell carcinoma (1 paper, 2023). "MMP-7 expression may affect the distal recurrence rate and disease-specific survival rate of HPV-positive oropharyngeal squamous cell carcinoma." (PMID 36941602, 2023).
oropharyngeal tumour (1 paper, 2014). "Samples from 61 patients diagnosed with oropharyngeal tumour were studied by immunohistochemistry against MMP-2, MMP-7, MMP-9 and MMP-13." (PMID 26019601, 2014).
osteonecrosis (1 paper, 2021). A none disease characterized by death of bone tissue due to a lack of blood supply. "Furthermore, another study also indicated that oral administration of Ok-PDRN inhibited the expression of IL-1β, matrix metalloproteinase (MMP)-3, and MMP-7, as well as production of inflammatory mediators including COX-2, prostaglandin E2 (PGE2), and TNF-α in an MIA-induced osteonecrosis model." (PMID 34067499, 2021).
peripheral nerve injury (1 paper, 2019). Injury to a peripheral nerve. "our current study revealed the promoting effect of MMP7 on Schwann cell migration and peripheral nerve regeneration, benefited the understanding of cellular and molecular mechanisms underlying peripheral nerve injury, and thus might facilitated the treatment of peripheral nerve injury." (PMID 31791378, 2019).
pneumococcal infection (1 paper, 2016). Infections with bacteria of the species streptococcus pneumoniae. "On the other hand, MMP-7 expression in the lungs can be upregulated by pneumococcal infection, which indicates the pivotal role of MMP-7 in the pathophysiology of lung infection." (PMID 27293304, 2016).
psychosis (1 paper, 2018). "For data from the same subjects presently studied we previously reported that proteins involved in the plasminogen pathway, including MMP7 and Factor 7, predicted psychosis conversion." (PMID 29875399, 2018).
pterygium (1 paper, 2021). A wedge-shaped fibrovascular lesion arising from the bulbar conjunctiva and extending to the cornea. "MMP3 was the only MMP/TIMP gene upregulated in pterygium, and only modestly, while MMP2, MMP7, MMP10, and MMP25 were downregulated." (PMID 34769520, 2021).
pulmonary TB (1 paper, 2015). "The collagenases, MMP-1 and MMP-8, were elevated in plasma of patients with pulmonary TB relative to healthy controls, and MMP-7 (matrilysin) and MMP-9 (gelatinase B) were also increased." (PMID 25635689, 2015). "However, the median MMP-7 value in respiratory symptomatics was higher at 66.3pg/ ml compared to 20.1pg/ml in both pulmonary TB and healthy controls, suggesting that plasma MMP-7 is elevated in a small proportion of patients with TB." (PMID 25635689, 2015).
relapsing-remitting MS (1 paper, 2009). "IFN-β is a promising treatment for MS and has been shown to repress MMP-7 and MMP-9 expression for patients with relapsing-remitting MS." (PMID 19267908, 2009).
retinal vein occlusion (1 paper, 2020). An occlusion of the retinal vein. "The AH concentrations of MMP-1, MMP-2, MMP-7, and MMP-9 are also elevated in patients with retinal vein occlusion." (PMID 32596291, 2020).
sarcoidosis (1 paper, 2022). Sarcoidosis is a multisystemic disorder of unknown cause characterized by the formation of immune granulomas in involved organs. "Some groups suggested both markers as IPF-specific predictors while another group reported higher serum and bronchoalveolar lavage fluid concentrations of MMP1 in sarcoidosis compared with higher concentrations of MMP7 in IPF in each fluid." (PMID 35203313, 2022). "In the present study, MMP7 showed an increased expression in FF not only from IPF but also from sarcoidosis lungs." (PMID 35203313, 2022). "One study also demonstrated an increased mRNA expression of MMP7 in FF from UIP patients within a compartment-specific analysis and one further group found increased plasma concentrations of MMP7 in sarcoidosis patients compared to healthy controls." (PMID 35203313, 2022). "However, data on MMP1 and MMP7 as potential serum biomarkers for IPF and/or sarcoidosis are controversial." (PMID 35203313, 2022).
sarcopenia (1 paper, 2020). Progressive decline in muscle mass due to aging which results in decreased functional capacity of muscles. "Although MMP-2 and MMP-9 seem to play major roles in the degradation of the extracellular matrix that leads to muscle wasting, the pathophysiological relevance of MMP-7 in the development and progression of sarcopenia is still mostly unknown." (PMID 32375664, 2020).
skin cutaneous melanoma (1 paper, 2022). "A remarkably higher expression of MMP7 in the tumor tissue of skin cutaneous melanoma (SKCM) was found compared to metastatic tissue (P < 0.01)." (PMID 35785154, 2022).
spinal muscular atrophy (1 paper, 2025). A motor neuron disease that affect the muscles, and characterized by muscle weakness and atrophy resulting from progressive degeneration and irreversible loss of the anterior horn cells in the spinal cord (i.e., lower motor neurons) and the brain stem nuclei. "Schoser and colleagues, using immunohistochemistry on muscle biopsies from a small cohort (n = 5) of patients with ALS, spinal muscular atrophy, and chronic axonal neuropathies, observed strong MMP-9 immunoreactivity—and to a lesser extent, MMP-2 and MMP-7—in all samples." (PMID 41009467, 2025).
stenosis (1 paper, 2025). "The elevated level of serum IFN-γ showed a significant correlation with a greater degree of disc herniation, whereas the increased serum concentration of MMP-7 was significantly associated with the presence of foraminal stenosis." (PMID 40844981, 2025). "The results demonstrated that the higher level of serum IFN-γ significantly correlated with a greater degree of HNP, while the elevated serum concentration of MMP-7 exhibited a significant correlation with the presence of foraminal stenosis." (PMID 40844981, 2025). "The higher level of serum IFN-γ significantly correlated with the severity of HNP (r = 0.436, P = 0.039) while the elevated serum concentration of MMP7 exhibited a significant correlation with the presence of foraminal stenosis (r = 0.436, P = 0.045)." (PMID 40844981, 2025).
tendinopathies (1 paper, 2013). "This prompted us to examine whether the increased collagen matrix contraction in response to HMC-1 could be due to increased expression of MMPs that are known to play a role in tendinopathies, including MMP1 and MMP7." (PMID 24517261, 2013). "In short, the present studies outline potential mechanisms by which mast cells could contribute to the pathogenesis of tendinopathy, and implicate the involvement of TGF-β1, PGE2, and MMPs (notably MMP1 and MMP7) in the response of tenocytes to mast cells." (PMID 24517261, 2013).
thrombosis (1 paper, 2024). "In addition, proteomic studies have identified MMP-7, MB, TM, and TIM-1 as biomarkers associated with atherosclerotic thrombosis and inflammation associated with OH." (PMID 38682102, 2024).
type 1 diabetes (1 paper, 2014). "We find that urine concentration of AGT, MMP‐7, and gremlin‐1 is low at the onset of type 1 diabetes and remains low in people who have intact kidney function after 30 or more years of type 1 diabetes." (PMID 24793984, 2014). "Furthermore, the finding of low urinary concentration of AGT, gremlin‐1, and MMP‐7 in new‐onset type 1 diabetes establishes a starting point for the trajectory of concentration of these proteins in the time course of DKD." (PMID 24793984, 2014). "Median urine MMP‐7/Cr (MMP‐7 concentration normalized to urine creatinine) in cases (6.0 ng/mg) was significantly different from those in controls (1.0 ng/mg) and participants with new‐onset type 1 diabetes (0.9 ng/mg)." (PMID 24793984, 2014). "We measured urine AGT, gremlin‐1, and MMP‐7 in individuals with type 1 diabetes and prevalent DKD (n = 20) or longstanding (n = 61) or new‐onset (n = 10) type 1 diabetes without DKD." (PMID 24793984, 2014). "The primary finding of this study is that urine AGT, MMP‐7, and gremlin‐1 concentration are markedly elevated in people with type 1 diabetes and DKD, compared with those with recently diagnosed type 1 diabetes or those with longstanding type 1 diabetes without DKD." (PMID 24793984, 2014).
uremia (1 paper, 2023). A clinical syndrome associated with the retention of renal waste products or uremic toxins in the blood. "In addition, as a member of the matrix metalloproteinase family that is typically involved in extracellular matrix degradation, Mmp7 function has been linked to tissue repair, transepithelial influx of neutrophils, and platelet activation during uremia." (PMID 37039638, 2023).
tumor (564 papers, 2002 to 2026). "Matrix metalloproteinase-7 (MMP-7) has also been implicated: MMP-7 promotes tumor cell detachment by degrading extracellular matrix components, facilitating their release into alveolar spaces and eventual reattachment to nearby structures." (PMID 41154429, 2025). "In a murine mammary carcinoma model, the vaccine encoding MMP-7 alone demonstrated considerable anti-tumor effects, characterized by reduced tumor growth, increased T cell infiltration, and prolonged survival." (PMID 39081320, 2024). "Both CD14+APOE+ cells and MMP7+ tumour cells were associated with poorer survival outcomes and immunotherapy therapy response, underscoring their potential as therapeutic targets." (PMID 39187937, 2024). "In order to confirm the presence of CD14+APOE+ cells and MMP7 tumour cells in close proximity, we determined the association between MMP7 and CD14 as well as APOE in a substantial group of NSCLC patients." (PMID 39187937, 2024). "Both CD14+APOE+ cells and MMP7+ tumour cells were associated with poorer survival outcomes and unfavourable immunotherapy response, underscoring their potential as biomarkers in NSCLC." (PMID 39187937, 2024). "Single nucleotide polymorphism (SNP) of promoter sites of the MMP7 gene has been shown to cause alteration in gene expression, hence resulting in changes in susceptibility to various diseases and tumor development." (PMID 38638796, 2024). "In the tumor compartment, responders showed significant upregulation of genes encoding matrix metalloproteinase (MMP7) and FN1 proteins." (PMID 38378868, 2024). "MMP-7 is also linked to clinicopathological aspects such as tumor stage by predicting the histological grade of the tumor." (PMID 37513440, 2023). "Matrix metallopeptidase 7 has been implicated in invasion and metastasis of tumor cells and is mainly expressed in epithelial cells." (PMID 37196797, 2023). "We further investigated the association between VEGFA/CTNNB1/MMP7/CD44 oncogenic expressions with selected immune cells in the tumor microenvironment (TME)." (PMID 36672201, 2023). "The previous studies showed that the MMP-7 expression has been closely associated with tumor invasion and metastasis." (PMID 37666882, 2023). "The proinflammatory protease MMP7 is associated with breakdown of the extracellular matrix, wound healing and tumor metastasis." (PMID 37063842, 2023). "Abnormally high expression of the gene encoding MMP-7 can promote tumor progression by inhibiting cancer cells’ apoptosis, reducing cell adhesion, and inducing angiogenesis." (PMID 37513440, 2023). "CTCL patients had higher circulating levels of IL-6, IL-8, IL-10, TGFβ, PGE2 and MMP7 which are factors released by tumor-associated macrophages in tumor microenvironment." (PMID 36059695, 2022). "Numerous studies have demonstrated that MMP-7 plays an important role in multiple processes associated with tumor progression, including cell growth, invasion, metastasis, and angiogenesis." (PMID 35496040, 2022). "We previously found preoperative serum and urine MMP-7 levels to be significantly associated with a higher tumour stage and the presence of lymph node metastases in BC." (PMID 35327500, 2022). "MMP-7 expression was positively associated with tumor size, invasion and microvessel density and matched the TNM classification." (PMID 35163805, 2022). "In summary, MMP-7 is a serum marker that seems to be directly associated with the presence of highly aggressive tumours, and represents a promising preoperative prognostic marker for UTUC." (PMID 35327500, 2022). "Among different MMPs, an MMP-7 gene polymorphism has been found to be associated with H. pylori infection status, gastric ulceration, tumor progression and survival of patients." (PMID 35163805, 2022). "IL-17 can promote epithelial mesenchymal transition and tumor cell invasion by inducing the expression of MMP7 in PCa cells, disrupting the E-calmodulin/β-linked protein complex, and releasing β-linked protein." (PMID 36452480, 2022).